TMEM63C (transmembrane protein 63C)
Description:
Acts as an osmosensitive cation channel preferentially activated upon hypotonic stress. In contrast to TMEM63B, does not show phospholipid scramblase activity. Enriched in mitochondria-ER contact sites where it may regulate the metabolite flux and organelles' morphologies in response to osmotic changes. In particular may regulate mitochondrial motility and function in motor neuron axons. Required for the functional integrity of the kidney glomerular filtration barrier (By similarity).
Synonyms: hTMEM63C; C14orf171; CSC1; DKFZp434P0111; hsCSC1; SPG87
Tractability: Antibody: UniProt places it where antibodies can reach, with high confidence; its Gene Ontology location is reachable by antibodies, with high confidence; UniProt predicts a signal peptide or a membrane-spanning region.
Gene: Protein-coding gene on chromosome 14 (77,116,568 to 77,259,498, forward strand). Ensembl gene ENSG00000165548.
Subcellular location: Endoplasmic reticulum membrane; Cell membrane
Subcellular location (Human Protein Atlas): Centrosome
Gene Ontology:
Molecular function: calcium-activated cation channel activity; phospholipid scramblase activity; osmolarity-sensing monoatomic cation channel activity
Biological process: monoatomic cation transport; glomerular filtration; monoatomic cation transmembrane transport
Cellular component: endoplasmic reticulum membrane; lysosomal membrane; plasma membrane; membrane
Genetic constraint (gnomAD): Loss-of-function variants: 31 observed, 95.62 expected, observed/expected ratio (o/e) 0.32, 90% interval 0.24 to 0.44. The upper end of that interval is the gene's LOEUF score, 0.44, which puts it in group 1 of 6, group 1 being the genes least tolerant of losing a copy. Missense variants: 822 observed, 1,078 expected, observed/expected ratio (o/e) 0.76, 90% interval 0.72 to 0.81. Synonymous variants: 375 observed, 405.92 expected, observed/expected ratio (o/e) 0.92, 90% interval 0.85 to 1.01.
Homologues: Orthologues: chimpanzee TMEM63C (99% identical), macaque TMEM63C (98% identical), guinea pig TMEM63C (86% identical), dog TMEM63C (85% identical), pig TMEM63C (85% identical), mouse Tmem63c (83% identical), rat Tmem63c (83% identical), rabbit TMEM63C (81% identical), tropical clawed frog tmem63c (53% identical), zebrafish tmem63c (53% identical). Paralogues in human: TMEM63B (42% identical), TMEM63A (39% identical).
Diseases named in the same sentence as TMEM63C in open-access papers:
TMEM63C is named in the same sentence as 15 diseases in open-access papers, as found by Europe PMC text mining. Sharing a sentence is not in itself a finding about the gene and the disease. The quoted sentences say what the papers report.
focal segmental glomerulosclerosis (4 papers, 2019 to 2024). A renal disorder characterized by sclerotic lesions in the glomeruli. "TMEM63C plays an important role in mediating the glomerular filtration barrier in zebrafish, and patients with TMEM63C loss in podocytes exhibit specific focal segmental glomerulosclerosis." (PMID 35821338, 2023). "Patients with focal segmental glomerulosclerosis exhibited specific TMEM63C loss in podocytes." (PMID 30900988, 2019). "Loss of glomerular TMEM63C expression in podocytes of patients with focal segmental glomerulosclerosis (FSGS) provided strong evidence for translational relevance." (PMID 30900988, 2019). "Additionally, TMEM63C is considered a biomarker of focal segmental glomerulosclerosis (FSGS)." (PMID 36078146, 2022).
age-related macular degeneration (1 paper, 2022). Age-related loss of vision in the central portion of the retina (macula), secondary to retinal degeneration. "In a study on age-related macular degeneration, a suggestive association signal in TMEM63C was found, but its role in AMD pathogenesis is unknown." (PMID 36078146, 2022).
Alzheimer disease (1 paper, 2024). A progressive, neurodegenerative disease characterized by loss of function and death of nerve cells in several areas of the brain leading to loss of cognitive function such as memory and language. "TMEM63C has been implicated in many clinical diseases, such as Alzheimer’s disease." (PMID 39770537, 2024).
breast carcinoma (1 paper, 2024). "Then, it was found that the G. lucidum immunomodulatory protein FIP-glu significantly regulated the mRNA levels of risk genes and reversed the tumor-promoting activity of TMEM63C in breast cancer T-47D and MCF-7 cells." (PMID 39770537, 2024). "FIP-glu significantly regulated these risk genes, and attenuated the promoting effect of TMEM63C in breast cancer cells." (PMID 39770537, 2024). "The Cell Counting Kit (CCK-8) assay revealed that the breast cancer cell viability was significantly increased after TMEM63C overexpression compared to the control group (p < 0.0001)." (PMID 39770537, 2024). "To determine the role of TMEM63C in the malignant potential of breast cancer cells, we overexpressed this gene in the T-47D and MCF-7 cells." (PMID 39770537, 2024). "Based on ENCORI, TMEM63C RNA level was increased in breast cancer." (PMID 39770537, 2024). "Based on these results, we can speculate that TMEM63C promotes the growth and proliferation of breast cancer cells." (PMID 39770537, 2024). "The pro-tumorigenic effect of TMEM63C was first validated in breast cancer cells, and this gene may be a potential novel therapeutic target." (PMID 39770537, 2024). "The functions of TMEM63C in breast cancer have not been reported." (PMID 39770537, 2024). "The effect of TMEM63C on breast cancer cells has not been reported." (PMID 39770537, 2024). "Thus, TMEM63C was overexpressed in T-47D and MCF-7 cells, and it was found that the viability and clone formation ability were significantly improved, suggesting that TMEM63C may be a potential target in breast cancer treatment." (PMID 39770537, 2024).
kidney damage (1 paper, 2019). "Nevertheless, taken together with our experimental analysis, the data clearly support Tmem63c as a novel candidate for further translational research on kidney damage." (PMID 30900988, 2019). "To explore the potential clinical relevance of TMEM63C for kidney damage, we selected patients with FSGS because they mirror the disease pattern observed in the MWF model." (PMID 30900988, 2019). "Thus, we explored TMEM63C expression in patients with FSGS and healthy controls to evaluate its potential role for human kidney damage." (PMID 30900988, 2019).
microcephaly (1 paper, 2025). A congenital or acquired developmental disorder in which the circumference of the head is smaller than normal for the person's age and sex. "Biallelic variants in the transmembrane protein 63C (TMEM63C) gene, encoding a predicted osmo sensitive calcium‐permeable cation channel, cause individuals with SPG87 associated with microcephaly in some, but not all cases." (PMID 39932116, 2025).
pancreatic cancer (1 paper, 2024). "In cancer, a high expression level of TMEM63C was associated with a worse prognosis in patients with papillary thyroid carcinoma, and TMEM63C was negatively associated with high lymph node proportion in pancreatic cancer." (PMID 39770537, 2024).
thyroid cancer (1 paper, 2022). "Five survival‐related genes, TMEM63C, COL5A1, LOXL1, ADAMTS2, and LYSMD3 were identified; the expression of COL5A1 and LOXL1 was upregulated in PTC tissues and may be related to OS and PFS of thyroid cancer patients." (PMID 35152572, 2022).
tumor (3 papers, 2022 to 2024). "The results of cell viability and clone formation assays also indicated that TMEM63C overexpression partly recovered tumor growth in T-47D and MCF-7 cells." (PMID 39770537, 2024). "The tumor-promoting effect of a potential novel therapeutic target transmembrane protein 63C (TMEM63C) was investigated in vitro." (PMID 39770537, 2024). "TMEM63C could promote tumor viability, growth, and proliferation in vitro." (PMID 39770537, 2024). "COL5A1, LOXL1, and TMEM63C expression levels were significantly higher and LYSMD3 expression levels were significantly lower in tumor tissues than in the paired normal tissues." (PMID 35152572, 2022).
TMEM63C also shares sentences with these, for which no sentence is quoted: cancer (2 papers); hereditary spastic paraplegia (1); Intellectual disability (1); neuroblastoma (1); neurological disease (1); papillary thyroid carcinoma (1).